SCN11A (sodium voltage-gated channel alpha subunit 11)
Description:
Sodium channel mediating the voltage-dependent sodium ion permeability of excitable membranes. Assuming opened or closed conformations in response to the voltage difference across the membrane, the protein forms a sodium-selective channel through which sodium ions may pass in accordance with their electrochemical gradient. Involved in membrane depolarization during action potential in nociceptors which function as key relay stations for the electrical transmission of pain signals from the periphery to the central nervous system. Also involved in rapid BDNF-evoked neuronal depolarization.
Synonyms: PN5; SCN12A; Nav1.9; NaN; SNS-2; FEPS3; HSAN7
Tractability: Small molecule: an approved drug acts on it; it belongs to a druggable protein family. Antibody: UniProt places it where antibodies can reach, with high confidence; its Gene Ontology location is reachable by antibodies, with high confidence; UniProt predicts a signal peptide or a membrane-spanning region. PROTAC: a small molecule that binds it is known.
Target class: Voltage-gated ion channel; Voltage-gated sodium channel; Ion channel
Gene: Protein-coding gene on chromosome 3 (38,845,764 to 39,052,157, reverse strand). Ensembl gene ENSG00000168356.
Subcellular location: Cell membrane
Pathways (Reactome):
Developmental Biology: Interaction between L1 and Ankyrins
Muscle contraction: Phase 0 - rapid depolarisation
Gene Ontology:
Molecular function: voltage-gated sodium channel activity; monoatomic cation channel activity; monoatomic ion channel activity
Biological process: membrane depolarization during action potential; sensory perception of pain; cardiac muscle cell action potential involved in contraction; sodium ion transmembrane transport; action potential; action potential initiation; acute inflammatory response; artery development; axonogenesis; behavioral response to acetic acid induced pain; behavioral response to formalin induced pain; behavioral response to pain; calcitonin gene-related peptide receptor signaling pathway; calcium ion transmembrane transport; cAMP/PKA signal transduction; cell motility; cellular response to cold; chemosensory behavior; chronic inflammatory response; circadian rhythm; detection of mechanical stimulus involved in sensory perception; detection of mechanical stimulus involved in sensory perception of pain; detection of temperature stimulus involved in sensory perception of pain; G protein-coupled receptor signaling pathway; inflammatory response; and 23 more
Cellular component: extracellular exosome; plasma membrane; axon; voltage-gated sodium channel complex; axonal growth cone; C-fiber; cell body; membrane; neuronal cell body
Genetic constraint (gnomAD): Loss-of-function variants: 78 observed, 112.87 expected, observed/expected ratio (o/e) 0.69, 90% interval 0.57 to 0.83. The upper end of that interval is the gene's LOEUF score, 0.83, which puts it in group 3 of 6, group 1 being the genes least tolerant of losing a copy. Missense variants: 1,661 observed, 1,874.8 expected, observed/expected ratio (o/e) 0.89, 90% interval 0.85 to 0.92. Synonymous variants: 643 observed, 665.91 expected, observed/expected ratio (o/e) 0.97, 90% interval 0.9 to 1.03.
Homologues: Orthologues: chimpanzee SCN11A (99% identical), macaque SCN11A (95% identical), dog SCN11A (79% identical), pig SCN11A (78% identical), rat Scn11a (73% identical), mouse Scn11a (72% identical), guinea pig SCN11A (70% identical), rabbit SCN11A (61% identical). Paralogues in human: SCN5A (53% identical), SCN10A (53% identical), SCN2A (53% identical), SCN3A (53% identical), SCN9A (52% identical), SCN1A (52% identical), SCN8A (52% identical), SCN4A (49% identical), SCN7A (38% identical), CACNA1A (24% identical), CACNA1S (24% identical), CACNA1B (23% identical), and 14 more.
Diseases named in the same sentence as SCN11A in open-access papers:
SCN11A is named in the same sentence as 44 diseases in open-access papers, as found by Europe PMC text mining. Sharing a sentence is not in itself a finding about the gene and the disease. The quoted sentences say what the papers report.
painful (11 papers, 2015 to 2025). "Gain-of-function mutations in the human SCN11A-encoded voltage-gated Na+ channel NaV1.9 cause severe pain disorders ranging from neuropathic pain to congenital pain insensitivity." (PMID 26645915, 2015).
neuropathy (9 papers, 2009 to 2025). A disorder affecting the nervous system that manifests with pain, tingling, numbness, and/or muscle weakness. "The model of cold-induced mechanical allodynia in mice with the Scn11a p.R222S mutation is novel and useful for evaluating analgesic drugs for intractable neuropathies related to NaV1.9." (PMID 32970203, 2021). "We note, however, that mice with null mutation of Scn11a continue to show tactile allodynia in neuropathy models." (PMID 19228393, 2009). "It was reported that the gene (SCN11A) that codes for the voltage-gated sodium channel NaV1.9 were reduced after neuropathy induction but that PEMF 10-Hz treatment brought it back to near-normal levels." (PMID 35698680, 2022).
migraine (6 papers, 2013 to 2026). "In SCN11A, another common (25%) missense variant, rs33985936-T (p.Val909Ile), associates with overall migraine (OR = 1.041, P = 3.4 × 10−9)." (PMID 37884687, 2023). "Genome-wide association analyses of migraine and its subtypes identify new susceptibility loci, including rare variants with large effects implicating PRRT2, SCN11A and KCNK5." (PMID 37884687, 2023).
epilepsy (5 papers, 2014 to 2023). A brain disorder characterized by episodes of abnormally increased neuronal discharge resulting in transient episodes of sensory or motor neurological dysfunction, or psychic dysfunction. "We herein found two patients with epilepsy carrying gene variants in SCN11A: one patient was diagnosed with EE, with an unreported c.1646dupA frameshift variant in SCN11A from the patient's mother." (PMID 38174099, 2023). "SCN1A, SCN2A, SCN3A, SCN8A, SCN9A, SCN11A, and SCN1B sodium channel gene mutations were intimately associated with epilepsy and displayed significant heterogeneity in pathogenesis and clinical symptoms." (PMID 38174099, 2023).
endometriosis (4 papers, 2014 to 2021). The growth of functional endometrial tissue in anatomic sites outside the uterine body. "In women with active endometriosis, we discovered that the concentrations of mRNAs encoded by SCN11A, TRPA1, and TRPV1 were all significantly increased in the samples of peritoneum." (PMID 25029427, 2014). "FLT1 and SCN11A were up-regulated and GNLY was down-regulated, suggesting that endometriosis is associated with an inflammatory response." (PMID 33868805, 2021). "We have previously shown that the presence of endometriosis lesions leads to increased expression of nociceptive and inflammatory markers (Trpv1, Scn11A, and Cox-2) in DRGs and spinal cords and the brains of mice with endometriosis." (PMID 31291762, 2019). "We detected a significant increase in expression of EP2, COX-1 and both TRPV1 and SCN11A ion channels in the DRGs of mice with endometriosis." (PMID 28281561, 2017). "We believe this is the first study to detect differences in the expression of mRNAs encoded by the ion channels TRPA1, P2RX3, SCN9A, and SCN11A in the peritoneum and lesions of women suffering from CPP, some of whom had endometriosis." (PMID 25029427, 2014). "TRPV1, TRPA1, and SCN11A mRNAs were significantly higher in the peritoneum from women with endometriosis (P < .001, P < .01)." (PMID 25029427, 2014). "SCN9A (Nav1.7) was elevated in lesions from women with endometriosis (P < .05), whereas SCN11A was significantly higher in the peritoneum of women with CPP and endometriosis compared with the peritoneum of women with CPP alone (P < .001)." (PMID 25029427, 2014). "EP2, Cox-1, Scn11a and Trpv1 mRNA concentrations were significantly increased in dorsal root ganglia (DRG; clusters of cell bodies of afferent sensory neurons that transmit noxious stimuli from the periphery to the spinal cord) from endometriosis mice (p < 0.05); EP4 and Cox-2 were unchanged." (PMID 28281561, 2017). "In summary, the results of this study indicate that therapies targeting P2RX3 may be useful in treating CPP in women with a diverse range of painful etiologies, whereas women with active endometriosis could benefit from treatments targeting TRPV1, TRPA1, SCN9A, or SCN11A." (PMID 25029427, 2014).
erythromelalgia (4 papers, 2008 to 2025). A rare neurovascular peripheral pain disorder due to the intermittent blockage of the blood vessels, usually in the lower extremities or hands. "Recently, rare variants of genes other than SCN9a were described in patients with clinically verified erythromelalgia: those genes included SCN10A (Nav1.8), SCN11A (Nav1.9), SCN5A (Nav1.5), SCN7A (Nav2.1), SCN8A (Nav1.6), SCN1B (Nav β1 subunit), SCN3B (Nav β3 subunit), TRPA1, TRPV1, WNK1 and NGFR." (PMID 27598514, 2016).
familial episodic pain syndrome (4 papers, 2016 to 2025). "SCN11A variants are notably associated with familial episodic pain syndrome (FEPS), a severe pain disorder in early childhood." (PMID 39940809, 2025).
primary erythromelalgia (3 papers, 2015 to 2024). "Primary erythromelalgia is often caused by mutations in the SCN9A, SCN10A, and SCN11A genes, which encode for NaV1.7, NaV1.8, and NaV1.9, neuronal sodium channels." (PMID 39458034, 2024).
Pruritus (3 papers, 2020 to 2022). Pruritus is an itch or a sensation that makes a person want to scratch. "Compared to Scn11a+/+ mice, Scn11a+/L799P mice showed enhanced scratching bouts before skin lesions developed, indicating pruritus." (PMID 32817686, 2020). "Scn11a+/L799P mice exhibited insensitivity to pain, but sensitivity to pruritus." (PMID 35711274, 2022). "In the present study we explored whether Scn11a+/L799P mice develop also pruritus, muscle weakness, and changes in gastrointestinal transit time." (PMID 32817686, 2020). "First, we explored whether Scn11a+/L799P mice exhibit pruritus, changes in motor performance, changes in skeletal muscles and joints, and disturbances in intestinal dysmotility." (PMID 32817686, 2020).
glioma (2 papers, 2020 to 2025). A benign or malignant brain and spinal cord tumor that arises from glial cells (astrocytes, oligodendrocytes, ependymal cells). "There were several DEGs that were overexpressed in the French bulldogs that are not specifically implicated in glioma but belong to important gene families with known roles in glioma, including SCN11A, MAPK6, HOXD8, and PSMB1." (PMID 42135822, 2025).
COVID-19 (1 paper, 2022). A disease caused by infection with severe acute respiratory syndrome coronavirus 2. "The rs33985936 variant in the SCN11A gene, the only variant that was replicated in the COVID-19 HG cohort, showed significant association with platelet crit and platelet count in the UK Biobank data." (PMID 35328087, 2022).
depression (1 paper, 2024). "Pearson correlation analysis showed that the levels of TC and SCN11A were linked with the Hamilton Depression Rating Scales score." (PMID 38734669, 2024). "Based on the IPA database analysis, we proposed that SCN11A might serve as a link between low lipid levels and depression." (PMID 38734669, 2024). "Moreover, we found that the serum SCN11A level was significantly correlated to TC level (negatively) and depression severity (positively)." (PMID 38734669, 2024).
Hypertension (1 paper, 2014). The presence of chronic increased pressure in the systemic arterial system. "Examples of ion channel-annotated genes derived from the DBP phenotype include TRPM2 (cation channel), SCN11A (sodium ion channel), ITPR1 (Ca+2-release mediator), and, (implicated in hypertension." (PMID 25519358, 2014).
peripheral neuropathy (10 papers, 2015 to 2023). A disorder affecting the peripheral nervous system. "The SCN11A codes for the sodium channel Nav1.9 is expressed in peripheral pan-sensing neurons and visceral afferent nerves and has been proven to be a threshold channel that is associated with peripheral neuropathy." (PMID 38174099, 2023). "Recently, SCN9A, SCN10A, and SCN11A screening efforts in 393 patients with painful peripheral neuropathy revealed causative SCN11A mutations (L1158P and I381T)." (PMID 27224030, 2016). "Two participants diagnosed with small fibre neuropathy carried likely pathogenic variants, SCN10A p.Gly1662Ser and SCN11A p.Cys1543Tyr." (PMID 36895957, 2023).
psychiatric disorder (1 paper, 2024). A disorder characterized by behavioral and/or psychological abnormalities, often accompanied by physical symptoms. "We need to explore if SCN11A would distinguish MDD from other psychiatric disorders that are comparable." (PMID 38734669, 2024).
SCN11A also shares sentences with these, for which no sentence is quoted: channelopathies (7 papers); neuropathic pain (6); small fiber neuropathy (5); Headache (3); trigeminal neuralgia (3); diabetic neuropathy (2); neuroblastoma (2); allergic rhinitis (1); Arrhythmia (1); Chronic constipation (1); Cirrhosis (1); colon cancer (1); dysautonomia (1); Erythema (1); erythropoietic protoporphyria (1); Granuloma (1); Hirschsprung disease (1); inflammation (1); inflammatory bowel disease (1); Lesch-Nyhan syndrome (1); multiple sclerosis (1); neuroma (1); ovarian carcinoma (1); paroxysmal extreme pain disorder (1); peripheral nerve injury (1); Phonophobia (1); Photophobia (1); spinal muscular atrophy (1); vasculitis (1).